ALB (albumin)
Diseases named in the same sentence as ALB in open-access papers (continued):
Sharing a sentence is not in itself a finding about the gene and the disease.
cerebral infarction (41 papers, 2013 to 2026). An ischemic condition of the brain, producing a persistent focal neurological deficit in the area of distribution of the cerebral arteries. "Multicenter studies have shown that elevated ALB levels are associated with favorable nerve recovery, reduced cerebral infarction volume, and alleviated cerebral edema." (PMID 40376152, 2025). "Elevated triglycerides are also associated with serum albumin levels and they jointly reduce the mortality risk due to cerebral infarction." (PMID 36237188, 2022). "In conclusion, our study suggests that the serum albumin-to-creatinine ratio (sACR) may serve as a novel and accessible biomarker for identifying individuals at increased risk of silent cerebral infarction (SCI) and subsequent adverse cerebrovascular events." (PMID 40917659, 2025). "Through its antioxidant, anti-inflammatory, and antithrombotic properties, albumin plays a key protective role in resisting cerebral infarction." (PMID 40535510, 2025). "This study summarizes the nursing management of a patient with cerebral infarction and sacrococcygeal Stage 2 pressure ulcer, focusing on the effectiveness of local oxygen therapy combined with human albumin." (PMID 41323027, 2025). "This study provides evidence of a significant effect of the lactate-to-albumin ratio (LAR) as an independent determinant of mortality rates in patients with cerebral infarction, both within 30 days and 90 days." (PMID 38779217, 2024). "In this regard, the lactate-to-albumin ratio (LAR) is a valuable indicator for assessing overall mortality in patients with cerebral infarction." (PMID 38779217, 2024). "Experimental studies have demonstrated that albumin therapy had a variety of neuroprotective effects, such as improving neurological function and reducing the volume of cerebral infarction and brain edema in animals with AIS." (PMID 37287379, 2023). "Univariate analysis revealed that DAR, WFNS grade, Hunt–Hess grade, delayed cerebral infarction (DCI), age, neutrophil-to-lymphocyte ratio (NLR), and CRP/albumin ratio (CAR) were associated with unfavorable outcomes." (PMID 36552160, 2022). "We found I/R evoked Evans blue extravasation, albumin leakage, brain water content increase, cerebral blood flow decrease, cerebral infarction and neurological deficits, all of which were attenuated by l-THP treatment." (PMID 26059793, 2015). "Treatment with albumin improves behavior, reduces brain infarction and swelling, improves local cerebral blood flow and reduces blood-brain barrier permeability." (PMID 24194876, 2013). "The study showed that albumin could improve blood flow and glucose utilization in cerebral infarction." (PMID 37206105, 2023). "The result showed that age, cerebral infarction, antihypertensive drug use, antiplatelet and anticoagulant use, past surgical history, past medical history, smoking, drinking, and neutrophil percentage-to-albumin ratio were closely related to the prolonged LOS." (PMID 36750951, 2023). "Adenoviral Netrin-5 delivery in MCAO mice attenuated cerebral infarction, improved functional outcomes, reduced edema, and preserved BBB integrity, evidenced by diminished Evans blue extravasation and albumin leakage." (PMID 41688424, 2026). "The potential medicinal ingredients of ZTC mainly act on core targets such as ALB, AKT1, and IL-6, and then regulate related molecular pathways to achieve the effect of treating or delaying cerebral infarction." (PMID 35047043, 2022). "According to our findings, patients with stereotaxic surgery, less history of cardiovascular or prior cerebral infarction, GCS >8 before admission to the hospital for craniotomy, and a blood albumin value >3.5 g/dL have a higher chance of being successfully weaned off the ventilator within 14 days." (PMID 38758888, 2024).
cerebral infarction (continued). "dMCAO but not craniectomy caused neurodegeneration and cerebral infarction, but both procedures induced an appreciable increase in BBB permeability to Evans blue dye, fluorescein, and endogenous albumin but not to 10 kDa dextran-FITC, leading to cerebral edema." (PMID 36224001, 2022).
Hypoglycemia (41 papers, 2011 to 2025). A decreased concentration of glucose in the blood. "Severe hypoglycemia has proven to be an independent risk factor for eGFR reduction and increased urinary albumin excretion, aggravating the occurrence and development of kidney disease." (PMID 40114703, 2025). "Their findings indicated that the frequency of nocturnal hypoglycemia in patients with Deg had an association with low serum albumin levels." (PMID 38541176, 2024). "Factors associated with decreased incidence of hypoglycemia were admission levels of albumin (OR 0.360, 95% CI 0.320–0.406, p < 0.001), hemoglobin (OR 0.951, 95% CI 0.923–0.978, p = 0.001) and eGFR (OR 0.993, 95% CI 0.990–0.997, p < 0.001)." (PMID 36431329, 2022). "We have previously shown that low admission serum albumin level or a decrease in albumin level during hospital stay is associated with an increased risk of hypoglycemia among patients admitted to internal medicine departments, regardless of DM status." (PMID 36431329, 2022). "Both malnutrition risk, as measured by the NRS2002 and admission serum albumin were found to be predictive of hypoglycemia." (PMID 31398808, 2019). "Therefore, it may be necessary to consider the risk of nocturnal hypoglycemia based on albumin levels when using IDeg; however, the use of Gla-300 may be unaffected by albumin levels." (PMID 36624651, 2023). "In our study, HD patients with ALB levels below 37.35 g/L were particularly vulnerable to hypoglycemia during HD, according to the cut-off value analysis result." (PMID 41293049, 2025). "Albumin (ALB) levels were inversely related to hypoglycemia occurrence (OR = 0.84, 95% CI: 0.71–0.98, p < 0.05), and lower pre-HD glucose (GLU) was similarly associated with greater hypoglycemia risk (OR = 0.66, 95% CI: 0.44–0.97, p < 0.05)." (PMID 41293049, 2025). "For ALB, a threshold of 37.35 g/L identified 45.6% of hypoglycemia patients below this value compared to 10.5% of controls (p < 0.01)." (PMID 41293049, 2025). "Albumin, although significant, demonstrated a more complex relationship with hypoglycemia, as indicated by the SHAP values." (PMID 40162207, 2025). "The incidence of FI in NCU patients was notably high, with independent risk factors identified as age, GCS scores, APACHE II scores, feeding route, mechanical ventilation, hypoglycemia, and serum albumin levels." (PMID 39507904, 2024). "We show here that serum albumin is a significant predictor of hypoglycemia even after controlling for SCIC and baseline CKD." (PMID 36431329, 2022). "Further laboratory investigations indicated severe coagulopathy, raised APTT, elevated serum transaminase and bilirubin levels, hypoglycemia, an elevated ammonia value, and a low albumin level, favoring the diagnosis of AFLP over HELLP syndrome." (PMID 36276902, 2022). "A blood sample taken Day 87 revealed mature neutrophilia (14,190/μL), monocytosis (1620/μL), eosinophilia (410/μL), hypoglycemia (42 mg/dL), low albumin concentration (2.8 g/dL), and high concentrations of globulin (3.7 g/dL) and fibrinogen (892 mg/dL)." (PMID 35864921, 2022). "Results: 218 patients (mean age 77.4 ± 12.0 years, 63.3% female, mean albumin 3.13 ± 0.32 g/dL), of whom 27.9% had documented hypoglycemia during hospitalization were included." (PMID 31398808, 2019). "Their limited interaction while bound to albumin is not adequate to explain the increased risk of hypoglycemia in patients." (PMID 41368518, 2025). "ROC curve analysis of ALB, Cre, Urea, Glucose on hypoglycemia during HD." (PMID 41293049, 2025). "Especially, in patients with low serum albumin levels, Gla-300 could achieve a lower GV and decreased frequency of hypoglycemia than Deg." (PMID 38541176, 2024).
Hypoglycemia (continued). "In this study, 10% of the participants had hypoglycemia at the time of admission, total serum bilirubin was raised among 23%, albumin levels were low for age in 21%, while serum glutamic-oxaloacetic transaminase (S. SGOT) and serum glutamic pyruvic transaminase (S. SGPT) levels were raised in 35%." (PMID 36514594, 2022). "Such continued fluid leakage could be due to uncorrected hypoglycaemia, acidosis, low serum calcium, lowering of serum albumin or due to administration of either iv or oral hypotonic fluids in excess." (PMID 21356095, 2011). "However, the relationship between albumin levels and hypoglycemia warrants further investigation." (PMID 40162207, 2025). "In summary, this study highlights HD period, CVDs, ALB, Cre, Urea, and GLU as key factors for preventing hypoglycemia during HD." (PMID 41293049, 2025). "The co-variates were age, sex, day of inclusion, albumin level, albumin increase status, percentage of ONS completed from inclusion and hypoglycemia occurrence." (PMID 31398808, 2019). "Baseline laboratory parameters, including liver and kidney function tests and serum albumin, were recorded and were within the normal range in all children, ensuring that they did not have seizures due to electrolyte imbalance or hypoglycemia." (PMID 40688992, 2025). "While the NRS2002 was a strong predictor for patients without DM, serum albumin was found to be a stronger predictor of hypoglycemia among DM patients." (PMID 31398808, 2019). "Compared with septic patients without VAD, those patients with VAD had a higher rate of hypoglycemia (4.5% vs. 18.1%; P = 0.011) and a lower serum albumin levels (31.64 ± 6.68 vs 28.64 ± 6.25, P = 0.004)." (PMID 31370866, 2019). "However, total protein and albumin levels in the blood of KI mice were greater than those in the blood of wild-type (WT) mice, suggesting that hypoglycemia in KI mice was unlikely to be due to undernourishment." (PMID 41116055, 2025). "The results from the systematic review show that the administration of PN significantly improved the levels of ESR, cholesterol, total phospholipids, and serum albumin, without producing clinical symptoms of hypoglycemia, independent of the method of interruption." (PMID 31766687, 2019).
malaria (41 papers, 2006 to 2024). Malaria is a serious and sometimes fatal disease caused by a parasite that commonly infects a certain type of mosquito which feeds on humans. "Additional studies are required to investigate the underlying mechanisms driving these associations and validate the clinical utility of albumin levels in malaria patient management." (PMID 38702420, 2024). "In the PALUREA study, three host-related biomarkers were associated with severe malaria, namely a high level of procalcitonin and sTREM-1, and a low level of albumin." (PMID 32052207, 2020). "This study underscores the clinical significance of albumin as a potential biomarker for Plasmodium infection and the severity of malaria." (PMID 38702420, 2024). "Regarding the association with disease severity, thematic synthesis showed that severe malaria cases generally had decreased albumin levels across various regions." (PMID 38702420, 2024). "A comprehensive literature search was conducted across multiple databases, including Embase, Scopus, PubMed, MEDLINE, Ovid, and Google Scholar, to identify studies examining albumin levels in malaria patients." (PMID 38702420, 2024). "This comprehensive systematic review and meta-analysis aimed to elucidate the relationship between albumin levels and malaria severity." (PMID 38702420, 2024). "The thematic synthesis indicated that albumin levels in malaria patients varied significantly based on geographical location." (PMID 38702420, 2024). "(1992) measured vascular endothelium permeability by trans-capillary escape of radiolabeled albumin and the urinary albumin/creatinine ratio in adult Thai patients with severe malaria and patients with uncomplicated malaria." (PMID 37637466, 2023). "Severe malaria patients also had significantly greater trans-capillary escape of radio-labeled albumin than those with uncomplicated malaria." (PMID 37637466, 2023). "This is in accordance with the occurrence of high proteinuria (>1000 μg/mg of albumin/creatinine) in malaria infected mice with AKI, which is suggestive of glomerular pathology." (PMID 36004329, 2022). "Aspartate aminotransferase, urea, creatinine, albumin, hydroxybutyrate dehydrogenase, and ferritin are useful biochemical indicators in routine clinical practice to evaluate prognosis for imported malaria." (PMID 36439238, 2022). "In malaria, a variety of serum/plasma proteins bind to HZ crystals such as serum amyloid A, gelsolin, fibrinogen, albumin, and the lipopolysaccharide (LPS)-binding protein." (PMID 31905972, 2019). "Severe acidosis, defined as a standard base deficit corrected for albumin (SBDc) >8 mmol/L, was present in 23 of 60 (38%) severe malaria cases, and moderate acidosis (SBDc >3.3 and ≤8 mmol/L) was found in 28 (47%) cases." (PMID 30566600, 2019). "This is in line with previous reports showing that blood proteins such as apolipoprotein E, serum amyloid A, LPS binding protein, complement factor H, albumin, and fibrinogen that were found to be elevated in malaria individuals are able to bind to HZ." (PMID 31905972, 2019). "Here we compare the safety and efficacy of Gelofusine (a succinylated modified fluid gelatin 4% intravenous infusion) and albumin in children with severe malaria complicated by metabolic acidosis." (PMID 16998584, 2006). "The vast burden of childhood death from malaria is borne by the resource-poor countries of Africa, where provision of albumin as a resuscitation fluid is complicated by both cost and lack of availability." (PMID 16998584, 2006). "In children with severe malaria, we have shown a consistent survival benefit of receiving albumin infusion compared to other resuscitation fluids, despite comparable effects on the resolution of acidosis and shock." (PMID 16998584, 2006). "Previous studies have shown that in children with severe malaria, resuscitation with albumin infusion results in a lower mortality than resuscitation with saline infusion." (PMID 16998584, 2006).
malaria (continued). "A separate meta-analysis of five studies found significantly lower albumin levels in patients experiencing severe malaria relative to those with less severe forms of the disease (P < 0.001, SMD = -0.66, 95% CI - 1.07 to - 0.25), I2: 73%, random effects model, 5 studies)." (PMID 38702420, 2024). "The findings suggest that albumin level monitoring could be crucial in managing malaria patients, especially in assessing disease severity and tailoring treatment approaches." (PMID 38702420, 2024). "The small size of PfHRP2/pLDH suggests that they may be freely excreted in urine, since the kidney has been implicated in falciparum malaria, leading to the release of specific malaria proteins and even larger molecules such as albumin." (PMID 34022958, 2021). "Also significant reduction of albumin level (P = 0.027) was observed among khat chewer malaria patients." (PMID 26173100, 2015). "Higher level of liver enzymes and other biomarkers such as lower level of albumin and higher level of total bilirubin observed in blood serum of khat chewer malaria patients could be accounted by their chronic exposure to khat." (PMID 26173100, 2015). "Patients with severe malaria were significantly more likely to have had temperature >38.5°C, white blood cell counts >10×109/μL, presence of schizonts in the peripheral blood smears, and albumin concentration of <3.5 g/dL at the time of admission." (PMID 23951178, 2013). "Albumin was equally detected in the binding or whole sample from control or malaria patients." (PMID 22028888, 2011). "Although it could be argued that further exploration of the optimal treatment regimes for patients with severe malaria acidosis should focus on albumin, there are reasons for caution in reaching this conclusion." (PMID 16998584, 2006). "In the trial reported here, carried out in Kenya's Kilifi District Hospital between 2004 and 2006, 88 children admitted with severe malaria were assigned to receive either albumin solution (a colloid solution made from blood protein) or Gelofusine (a synthetic colloid)." (PMID 16998584, 2006). "Contribution to the evidence: This study adds data suggesting that fluid resuscitation with albumin solution, as compared to Gelofusine, may reduce the chance of death in children with severe malaria." (PMID 16998584, 2006). "Albumin may act to improve microvascular perfusion in malaria through its rheological effects as well as by volume expansion and influencing fluid shifts across the endothelium." (PMID 16998584, 2006). "Neurological sequelae were more common in survivors receiving albumin in this and our previous trial, but their frequency accords with all other case series of severe malaria known to us, which have consistently documented ~12% neurological impairment rates in survivors." (PMID 16998584, 2006). "Interestingly, a randomized trial comparing HSA and saline in children with malaria demonstreated that the mortality rate was significantly lower among patients who received albumin than among those who received saline (3.6% vs 18%; 95% CI 1.2–24.8; p = 0.013)." (PMID 36979511, 2023). "However, the authors observed no consistent association between AF-albumin level, malaria infections, malaria-specific antibody, or lymphoproliferative responses." (PMID 33139646, 2020). "Thus, the respective molecular weight of PfHRP2 and pLDH is less than half the molecular weight of albumin, so if albumin is excreted in urine in uncomplicated malaria, then PfHRP2 and pLDH could be freely excreted as well." (PMID 32993649, 2020). "In the Malawi (iLiNS-DYAD) cohort, we examined correlations between maternal Cu concentration and common analytes including APRs (CRP, AGP, and ALB) and infections (HIV and malaria) in 1239 samples collected at enrollment." (PMID 37890672, 2024).